EEF1A2 (eukaryotic translation elongation factor 1 alpha 2)
Diseases named in the same sentence as EEF1A2 in open-access papers (continued):
Sharing a sentence is not in itself a finding about the gene and the disease.
prostate carcinoma (13 papers, 2010 to 2026). A carcinoma that arises from epithelial cells of the prostate gland. "We have previously shown that eEF1A2 is a potential hallmark for prostate transformation and progression due to its inappropriate expression in prostate cancer cells." (PMID 35456960, 2022). "Here, we focus on the expression of EEF1A1/A2 in a panel of human prostate cancer cells demonstrating that the switch-on of EEF1A2 gene expression associates with prostate cell transformation." (PMID 22095224, 2012). "In addition, EEF1A2 has been demonstrated to serve as an autonomous biomarker for the purpose of risk stratification in the context of prostate cancer." (PMID 38172654, 2024). "The overexpression of EEF1A2 was found in prostate cancer and could be used as a biomarker for its risk-stratification." (PMID 35300699, 2022). "siRNA-based knockdown of EEF1A2 resulted in a reduction in migratory abilities of metastatic prostate cancer cell line PC3." (PMID 38172654, 2024). "In the context of prostate cancer, the overexpression of EEF1A2 in metastatic prostate cancer suggests its potential as a tissue-based biomarker for monitoring cancer progression and cell transformation." (PMID 38172654, 2024). "In a study conducted to explore the pro-tumorigenic role of EEF1A2 in prostate cancer, siRNA-mediated suppression of eEF1A2 protein resulted in reduced proliferation rate and colony formation in two prostate cancer cell lines, DU-145 and PC-3." (PMID 38172654, 2024). "Overexpression of eEF1A2 has been observed in prostate cancer and intrahepatic cholangiocarcinoma, including tumors in the ovary, breast, and lung." (PMID 37051183, 2023). "Another study in prostate cancer DU-145 and PC-3 cells also showed that eEF1A2 silencing increased the caspase-3 protein accompanied by an enhanced apoptosis rate." (PMID 37051183, 2023). "In contrast to eEF1A2, the contribution of eEF1A1 to the phenotypic and molecular changes in human prostate cancer is far less clear." (PMID 35456960, 2022). "Here, we dissect the contribution of the two constitutive forms, that is, eEF1A1 and eEF1A2 in prostate cancer." (PMID 22095224, 2012). "In particular, eEF1A2 levels resulted significantly increased in all prostate cancer cell lines with the highest levels detected in LNCaP (LNCaP, P=0.000005; DU-145, P=0.000001; and PC-3, P=0.0000007 vs PZHPV-7)." (PMID 22095224, 2012). "This opens the possibility to consider eEF1A2 content/distribution useful for a more defined prostate cancer diagnosis." (PMID 22095224, 2012). "In conclusion, the results here presented support the concept that EEF1A2 switch-on is a feature of prostate cancer, assigning to EEF1A1 a minor involvement as potential marker of cancer." (PMID 22095224, 2012). "Together, the data collected from these different models of prostate tumour in vitro strongly suggest that the eEF1A2 levels correlate with the transformation of prostate cancer cells." (PMID 22095224, 2012). "The overexpression of EEF1A2 gene in cancer cells merely resulted from the switch-on of the gene without a significant gene amplification likely indicating that the activation and modulation of EEF1A2 transcription is the most remarkable event in prostate cancer cells." (PMID 22095224, 2012). "In addition, eEF1A2 has been shown to be an independent biomarker for prostate cancer risk stratification, because its overexpression is negatively associated with recurrence-free survival." (PMID 35456960, 2022). "EEF1A2 was subsequently found to support tumor cell survival via abrogation of apoptosis in HCC, mouse plasmacytomas, and prostate cancer." (PMID 38172654, 2024). "However, the most evident result of our investigation is the dramatic up-regulation of the expression of EEF1A2, but not of EEF1A1, in the prostate cancer lines at the mRNA and protein levels, compared with the non-tumourigenic prostate PZHPV-7 cells." (PMID 22095224, 2012).
multiple myeloma (9 papers, 2010 to 2022). "This cytotoxic peptide interacts with elongation factor 1-alpha 2 (eEF1A2), which is overexpressed in myeloma cells, leading to a proapoptotic event." (PMID 35740630, 2022). "It is an inhibitor of eukaryotic translation elongation factor 1 alpha 2 (eEF1A2) and is used clinically to treat multiple myeloma." (PMID 36182930, 2022). "The most potent antiviral tested was plitidepsin, which targets the eukaryotic Elongation Factor 1A2 (eEF1A2) and has been previously used for the treatment of multiple myeloma." (PMID 33841165, 2021). "We demonstrate that plitidepsin, an antitumor agent of marine origin that has successfully completed a phase-III clinical trial for multiple myeloma, exerts its antitumor activity by targeting eEF1A2." (PMID 27713531, 2016). "Cases of human multiple myeloma expressed significantly higher levels of EEF1A2 transcripts than normal bone marrow plasma cells." (PMID 20505761, 2010). "Our curiosity was heighted by the findings that EEF1A2 was also expressed at high levels in some cases of multiple myeloma (MM), a plasma cell neoplasm of humans, but not by normal plasma cells or B cells in either species." (PMID 20505761, 2010).
epileptic encephalopathies (8 papers, 2016 to 2026). "De novo heterozygous missense mutations in EEF1A2, encoding neuromuscular translation-elongation factor eEF1A2, are associated with developmental and epileptic encephalopathies." (PMID 38179821, 2024). "In this region, three genes including KCNQ2, EEF1A2, and CHRNA4 were related to dominant epileptic encephalopathy, and KCNQ2 is the key gene." (PMID 35557555, 2022).
hepatocellular carcinoma (8 papers, 2015 to 2024). A malignant tumor that arises from hepatocytes. "Moreover, elevated levels of EEF1A2 in hepatocellular carcinoma biopsy samples suggest its potential as a diagnostic marker." (PMID 38172654, 2024). "According to current research reports, silencing eEF1A2 significantly reduced the occurrence of hepatocellular carcinoma by inhibiting the PI3K/Akt/NF-κB signaling transduction." (PMID 38957390, 2024). "A study of hepatocellular carcinoma (HCC) cells from patients showed that siRNA-mediated knockdown of eEF1A2 expression diminished the activation of both Akt and mTOR signaling, suggesting that eEF1A2 is an upstream inducer of PI3K." (PMID 37051183, 2023). "In cases of hepatocellular carcinoma (HCC), overexpression of TIM exerted oncogenic function through CHEK2 and eukaryotic elongation factor 1A2 (EEF1A2)." (PMID 32499870, 2020).
pancreatic ductal adenocarcinoma (6 papers, 2017 to 2024). An infiltrating adenocarcinoma that arises from the epithelial cells of the pancreas. "In pancreatic ductal adenocarcinoma elevated expression of EEF1A2 was associated with nodal metastasis, perineural invasion and worse prognosis." (PMID 28923030, 2017). "A study on pancreatic ductal carcinoma (PDA) showed 77.8% positive immunoreactivity for EEF1A2, and no expression was observed in normal pancreatic tissue." (PMID 38172654, 2024).
cervical cancer (5 papers, 2018 to 2024). A primary or metastatic malignant neoplasm involving the cervix. "A sole investigation into EEF1A2 expression in cervical cancer unveiled various alterations among cervical cancer patients, including missense mutations, splice mutations, amplifications, and heightened mRNA levels." (PMID 38172654, 2024). "Analysis of the cBioPortal database showed that 18 of 297 cervical cancer patients had eEF1A2 gene changes, including missense mutation, splice mutation, amplification, and messenger RNA increase." (PMID 36637958, 2023). "The eEF1A2 copy number in cervical cancer tissues and chronic cervicitis tissues was determined by real-time fluorescence quantitative polymerase chain reaction." (PMID 36637958, 2023). "Changes in eEF1A2 expression in cervical cancer tissues were analyzed using cBioPortal, a portal for cancer genomics analysis." (PMID 36637958, 2023). "The expression of the eEF1A2 gene in cervical cancer and its relationship with patient survival were analyzed using gene expression profile interactive analysis." (PMID 36637958, 2023). "Analysis of the relationship between the expression of eEF1A2 in cervical cancer and the survival of patients by the database of The Human Protein Atlas." (PMID 36637958, 2023). "Real-time fluorescent quantitative PCR was used to detect the copy number of the eEF1A2 gene in cervical cancer tissues, chronic cervicitis tissues, and normal cervical tissues." (PMID 36637958, 2023). "In preliminary work, we performed immunohistochemistry experiments and found that the expression level of the eEF1A2 protein was significantly higher in cervical cancer tissue than in chronic cervicitis tissue." (PMID 36637958, 2023). "The GEPIA database was used to analyze the expression of eEF1A2 in various tumors, including cervical cancer, and in normal samples." (PMID 36637958, 2023). "The GEPIA database was used to analyze the expression of the eEF1A2 gene in cervical cancer and its relationship with patient survival." (PMID 36637958, 2023). "Analysis of the genetic changes of eEF1A2 in cervical cancer tissues using cBioPortal showed that among 297 cervical cancer patients analyzed, 18 showed eEF1A2 gene changes, including missense mutations, splice mutations, amplifications, and messenger RNA increase." (PMID 36637958, 2023). "The relationship between the expression of eEF1A2 protein and the clinical stage, pathological grade, and patient survival of cervical cancer was analyzed by the database: The Human Protein Atlas, an integrated repository portal for tumor-immune system interactions." (PMID 36637958, 2023). "In summary, the expression of eEF1A2 protein in cervical cancer has no statistical significance with the clinical stage, pathological grade and survival of patients by immunohistochemical database analysis (P > .05)." (PMID 36637958, 2023). "The eEF1A2 gene expression level was not correlated with the survival of cervical cancer patients (P > .05)." (PMID 36637958, 2023).
plasmacytoma (5 papers, 2010 to 2024). Plasmacytoma is a localized mass of neoplastic monoclonal plasma cells that represents approximately 5% of all plasma cell neoplasms. "Transcriptional profiling of a spectrum of primary mouse B cell lineage neoplasms showed that transcripts encoding EEF1A2 were uniquely overexpressed in plasmacytomas (PCT), tumors of mature plasma cells." (PMID 20505761, 2010). "Previously, eEF1A2 has been shown to possess the anti-apoptosis effect in mouse plasmacytoma cell lines via activation of PI3K/Akt." (PMID 32425742, 2020). "eEF1A2 has also been shown to involve a reduction of apoptosis in mouse plasmacytoma cell lines via activation of Akt." (PMID 26981313, 2016). "In mouse plasmacytomas, Eef1a2 regulates tumor growth and proliferation through activation of the JAK/STAT and Akt signaling pathways." (PMID 26981313, 2016). "Our interest in EEF1A2 was kindled by results from gene expression profiling of primary mouse B cell lineage tumors that revealed uniquely high expression in plasmacytomas (PCT), neoplasms of mature plasma cells." (PMID 20505761, 2010). "EEF1A2 is a translation elongation factor gene that was previously shown to promote survival of mouse plasmacytoma cells, whereas EIF4E3, RND3/RhoE and FAM129A/Niban encode proteins that participate in various facets of cap-dependent translation initiation (described in more detail below)." (PMID 27626179, 2016). "In another study with mouse plasmacytomas, i.e., tumors of mature plasma cells, EEF1A2 knockdown expression decreased IL-6-mediated activation of STAT3 and AKT pathways, leading to a decrease in proliferation of plasmacytomas (PCT) cell lines with delayed cell-cycle entry." (PMID 38172654, 2024).
glioma (4 papers, 2007 to 2023). A benign or malignant brain and spinal cord tumor that arises from glial cells (astrocytes, oligodendrocytes, ependymal cells). "IL-8 was involved in macrophage polarization from M1 to M2 in glioma, and was founded to be up-regulated in EEF1A2-overexpressed U87-MG cell line." (PMID 34446611, 2021). "The results showed that the eEF1A2 gene was highly expressed in breast invasive carcinoma, pancreatic adenocarcinoma, and pheochromocytoma and paraganglioma tissues, and was expressed at low levels in glioblastoma multiforme, brain lower grade glioma, and other tissues." (PMID 36637958, 2023). "Glioblastoma and glioma dataset revealed that EEF1A1, EEF1G, EEF1D and EEF2 were significantly overexpressed in tumor tissues whereas EEF1A2 was significantly downregulated." (PMID 29342219, 2018). "Some genes already described as related to glioma's invasion capacity by microarray studies such as SPOCK1, BCL2L2, EEF1A2 and TMEFF1 also appeared in the 50 first best triples." (PMID 17519038, 2007).
lung adenocarcinoma (4 papers, 2018 to 2025). A carcinoma that arises from the lung and is characterized by the presence of malignant glandular epithelial cells. "It was found that there is a significant correlation between elevated protein levels and amplification in gene copy number or increased transcript levels of the EEF1A2 gene in lung adenocarcinoma cell lines (H23, H229, H1792, SK-LU-1, H522, and H1563)." (PMID 38172654, 2024). "In this study, we aimed to elucidate the oncogenic function of EEF1A2 in the metastasis of lung adenocarcinoma (LUAD)." (PMID 33473168, 2021). "In all the five studies, EEF1A2 was elevated significantly in lung adenocarcinoma subtype." (PMID 29342219, 2018). "Another study reported that EEF1A2 increased epithelial–mesenchymal transformation (EMT) and promoted metastasis in vitro and in vivo in lung adenocarcinoma (LUAD)." (PMID 38172654, 2024). "In addition, EEF1A2 interacts with HSP90AB1 to promote lung adenocarcinoma metastasis, and DSCC1 interacts with HSP90AB1 to enhance the proliferation and metastasis of lung adenocarcinoma cells." (PMID 41209079, 2025). "The analysis conducted on the TCGA dataset for lung adenocarcinoma (LUAD) and lung squamous cell carcinoma (LUSC) revealed increased levels of EEF1A2 expression, while no significant change was observed in the expression of EEF1A1." (PMID 38172654, 2024).
non-small cell lung carcinoma (4 papers, 2016 to 2024). A group of at least three distinct histological types of lung cancer, including non-small cell squamous cell carcinoma, adenocarcinoma, and large cell carcinoma. "Furthermore, in stage I non-small cell lung cancer patients, EEF1A2 has been identified as a surrogate marker for poorer prognosis." (PMID 38172654, 2024). "Controversially negative staining for EEF1A2 was a predictor for poor outcome in patients with non-small cell lung cancer." (PMID 28923030, 2017).
Parkinson disease (4 papers, 2021 to 2026). A progressive degenerative disorder of the central nervous system characterized by loss of dopamine producing neurons in the substantia nigra and the presence of Lewy bodies in the substantia nigra and locus coeruleus. "It is noteworthy that silencing EEF1A2 decreases viability and increases apoptosis in Parkinson’s disease." (PMID 35013140, 2022). "To determine how eEF1A2 may play a role in the Akt/mTOR signaling pathway in this Parkinson's disease model, we performed eEF1A2 silencing in SH-SY5Y cells before MPP+ treatment." (PMID 37051183, 2023). "The role of eEF1A2 in the pathogenesis of Parkinson's disease (PD) has yet to be investigated." (PMID 37051183, 2023). "Our recent study showed that eEF1A2 knockdown aggravated α-synuclein accumulation and reduced mitophagy, which resulted in decreased viability, increased apoptotic nuclei, and increased caspase-3/7 in an SH-SY5Y cell model of Parkinson's disease (PD)." (PMID 37051183, 2023).
clear cell carcinomas (3 papers, 2007 to 2024). "The finding that eEF1A2 overexpression at the protein level is often associated with clear cell carcinomas is intriguing." (PMID 17437010, 2007). "In this set of tumours, the expression of eEF1A2 is highly significantly associated with the clear cell carcinoma subtype when compared with all other tumour sub-types combined (P<0.0012, Fisher's exact test)." (PMID 17437010, 2007). "The key findings of this study were that a higher proportion of clear cell carcinomas overexpress EEF1A2 compared with other histological subtypes." (PMID 38172654, 2024). "We show that while overexpression of eEF1A2 is seen at both the RNA and protein level in up to 75% of clear cell carcinomas, it occurs at a lower frequency in other histological subtypes." (PMID 17437010, 2007). "Furthermore, it was shown that eEF1A2 overexpression was present in 75% of clear cell carcinomas, which is higher than in other histological subtypes." (PMID 35718769, 2022).
glioblastoma (3 papers, 2018 to 2024). The most malignant astrocytic tumor (WHO grade IV). "Our investigations have further elucidated the significant role of EEF1A2 expression levels in neuroblastoma and glioblastoma cell lines." (PMID 38172654, 2024). "EEF1A2 could increase migration and invasion in neuroblastoma and glioblastoma cell lines in a PI3K-dependent manner." (PMID 38172654, 2024). "Similarly, in Sun’s study, EEF1A2 was quite evidently under-expressed in glioblastoma, compared to normal tissue." (PMID 29342219, 2018).
leukemia (3 papers, 2023 to 2024). A malignant (clonal) hematologic disorder, involving hematopoietic stem cells and characterized by the presence of primitive or atypical myeloid or lymphoid cells in the bone marrow and the blood. "Altogether, our data reveal that a syntenin‐deficient environment may ultimately lead to the activation of EEF1A2/AKT/RPS6 molecular pathways in AML cells, stimulating protein synthesis and enhancing cell survival, advantages educating the leukemia to become more aggressive." (PMID 37819151, 2023).
lymph node metastasis (3 papers, 1995 to 2025). "The results revealed that eEF1A2 is tightly correlated with lymph node metastasis and poor prognosis in patients with GBC." (PMID 41705259, 2025).
neuroblastoma (3 papers, 2016 to 2024). Neuroblastoma (NB) is the most common solid, extracranial childhood tumor. "Our recent study has demonstrated that MLIF exhibits neuroprotection in OGD-insulted SH-SY5Y neuroblastoma by targeting eEF1A2." (PMID 34557098, 2021).
pancreatic adenocarcinoma (3 papers, 2023 to 2024). "Also, high expression of EEF1A2 is associated with poor prognosis, but the TCGA dataset (PAAD) from GEPIA2 showed a negative hazard ratio for EEF1A2 and EEF1A1 in pancreatic adenocarcinoma." (PMID 38172654, 2024).
triple-negative breast carcinoma (3 papers, 2019 to 2020). An invasive breast carcinoma which is negative for expression of estrogen receptor (ER), progesterone receptor (PR), and human epidermal growth factor receptor 2 (HER2). "EEF1A2 expression is elevated in poor prognosis of triple negative breast cancers." (PMID 32751422, 2020). "No data are available about the role of eEF1A2 in Triple Negative Breast Cancers (TNBC)." (PMID 31220107, 2019).